GNRHR (gonadotropin releasing hormone receptor)
Diseases named in the same sentence as GNRHR in open-access papers (continued):
Sharing a sentence is not in itself a finding about the gene and the disease.
cancer (66 papers, 2011 to 2025). A tumor composed of atypical neoplastic, often pleomorphic cells that invade other tissues. "The most enriched pathways play vital roles in cancer biology, such as the Wnt signaling and gonadotropin-releasing hormone receptor pathways." (PMID 41226241, 2025). "In preclinical studies, GnRH derivatives have been used as targeting carriers in peptide-based drug delivery platforms, enhancing the selective delivery of payloads into cancer cells via GnRHR-mediated endocytosis." (PMID 40563508, 2025). "Though, targeted studies show its link with growth factor receptors and integrins, the mechanism of action of GnRH and GnRH receptor (GnRHR) in cancer cells is not fully understood." (PMID 35109816, 2022). "Several reports suggest that GnRHR expressed in cancer cells directly contributes to cancer progression, and GnRH analogs exert direct anti-cancer actions by modulating Gα subunits." (PMID 34743733, 2021). "Based on the evidence, cancer cell-expressing GnRHR is considered as a novel receptor-targeting anti-cancer strategy." (PMID 34743733, 2021). "GnRH-ICG exhibited the binding capacity in a panel of cancer cell lines with different expression levels of GnRHR." (PMID 32185134, 2020). "As the binding ligands of GnRHR, GnRH analogs (both agonists and antagonists) have been conjugated to various cytotoxic drugs and shown a high affinity for cancer cells." (PMID 32185134, 2020). "A significant number of studies on GnRHR-based therapy have substantiated its applicability, specificity, and safety in cancer targeting." (PMID 32185134, 2020). "Here, we demonstrate clear evidence of the lysosomal sequestration of GnRHR-targeted crizotinib–GnRH conjugates, a phenomenon which should be taken into account in the development of anti-cancer GnRH conjugates with therapeutic value." (PMID 31717403, 2019). "It is well known that several types of cancer cells maintain an elevated GnRHR expression, pointing to the role of GnRH/GnRHR system in the development of these tumors." (PMID 31717403, 2019). "It is generally accepted that synthetic GnRH analogues are able to deliver the conjugated drug into GnRHR-expressing cancer cells." (PMID 31717403, 2019). "The expression of gonadotropin-releasing hormone (GnRH) receptor (GnRHR) in some cancers is higher than in normal tissues." (PMID 29461120, 2018). "This approach is based on the fact that receptors for many regulatory ligands such as peptide hormones are overexpressed on the surface of various cancer cells including gonadotropin-releasing hormone receptors (GnRH-R)." (PMID 29719573, 2018). "Both hyperactivity (i.e., high doses of GnRH, ~100 nM) and inhibition of GnRHR can suppress cancer cell proliferation and induce apoptosis." (PMID 28439256, 2017). "In conclusion, we showed that different types of human prostate cell lines (normal, hyperplasia, and cancer) are sensitive to the antiproliferative effect of degarelix, a GnRHR antagonist." (PMID 25811175, 2015). "Gonadotropin-releasing hormone (GnRH) and its receptor (GnRHR) are both expressed by a number of malignant tumors, including those of the breast." (PMID 23176180, 2012). "In addition, GnRH and GNRHR have a confirmed relationship with cancer, providing the possibility of cancer treatment through targeting of these molecules." (PMID 34573523, 2021). "However, the precise role of GnRHR-mediated Gαs-cAMP signaling in cancer progression needs to be further clarified." (PMID 34743733, 2021). "Gonadotropin-releasing hormone receptor (GnRHR) is a G-protein coupled receptor found in the anterior pituitary’s gonadotroph membrane and many extra-pituitary tissues such as the ovary, placenta, breast, and cancer tissues." (PMID 34563259, 2021). "GnRHR expression in cancer cell lines was evaluated by western blot." (PMID 32185134, 2020). "Next, we incubated GnRHa-ICG with cancer cell lines with different GnRHR expression levels." (PMID 32185134, 2020).
cancer (continued). "This is essential information, because the restrained translocation and the relatively low amount of human GnRHR on the plasma membrane of cancer cells are common phenomena which could limit effective GnRHR targeting." (PMID 31717403, 2019). "According to the literature data on anti-cancer GnRH conjugates, we hypothesized that the GnRHR-targeted delivery of crizotinib might reduce side effects, improve efficacy, and even delay the development of resistance." (PMID 31717403, 2019). "Here, we demonstrate that both GnRH-III-Dau conjugates possess an efficient growth inhibitory effect on more than 20 cancer cell lines, whereby the biological activity is strongly connected to the expression of gonadotropin-releasing hormone receptors (GnRH-R)." (PMID 31557968, 2019). "Therefore, imbalances in the levels of GnRHR activity appear to modulate the rate of cancer cell proliferation and metastasis." (PMID 28439256, 2017). "Another recently developed approach to tackle challenging cancer types is based on connecting the chemotherapeutic agents with the peptide ligands which show a high affinity for receptors overexpressed in a tumor tissue, such as the gonadotropin releasing hormone receptor (GnRH-R)." (PMID 33445797, 2021). "In addition, the limited amount of GnRHR on the plasma membranes of cancer cells might be another restrictive factor, which is a less investigated part of GnRHR-targeted drug delivery and should be further investigated." (PMID 31717403, 2019). "These examples are GNRHR, FGF4, and FGF6, which have all been shown to play important roles in cancer biology." (PMID 38555407, 2024). "Furthermore, a growing number of studies have determined that GnRHR stimulation by GnRH analogs induces antiproliferative and antimetastatic effects in various types of tumors, therefore, presenting GnRHRs as a good candidate for therapeutic intervention for cancers." (PMID 37124730, 2023). "A similar approach, but with the use of the pNF-κB plasmid, along with the gonadotropin-releasing hormone receptor (GnRH-R) agonist triptorelin and the prodrug GCV, resulted in reduced cancer cell growth, both in vitro and in vivo in mice." (PMID 35805007, 2022). "In our model, Kiss1R, GnRHR, and LHR act as cancer suppressors by inhibiting proliferation and metastasis." (PMID 28439256, 2017). "Gonadotropin-releasing hormone (GnRH), also called luteinizing hormone releasing hormone (LHRH), and its relative receptor (GnRHR, LHRHR) are overexpressed in different types of cancer and present a limited expression in normal tissues." (PMID 25514225, 2014). "Although it has been proposed that GnRH analogs regulate not only well-established Gαq but also Gαs pathway in several extra-pituitary cells, pharmacological effects of Gαs-coupled GnRHR activation has not been studied in cancer cells." (PMID 34743733, 2021). "The limited success of GnRH conjugates indicates an insufficient understanding of the GnRH/GnRHR systems in cancers and the possible drawbacks of GnRHR targeting, which had not been highlighted previously." (PMID 31717403, 2019). "We detected GNRHR in 54%, LHCGR in 77% and FSHR in 0% of the cancer samples." (PMID 30400009, 2019). "For example, conjugates of GnRH analogs with chemotherapeutic drugs, delivery carriers, or imaging agents specifically deliver drugs or agents into GnRHR-positive cancer cells rather than GnRHR-negative cells." (PMID 29461120, 2018). "Owing to the selective expression of GnRHR in cancers but not in most normal tissues, GnRHR could be an effective theranostic target to guide the delivery of anticancer therapeutics and diagnostic agents into cancer cells." (PMID 40563508, 2025).
tumor (47 papers, 2007 to 2025). "Interestingly, the estrogen receptor (ER) locus and the gonadotropin-releasing hormone receptor (GnRHR) are associated with litter size in domestic farm animals and also expressed in many tumor types." (PMID 33209304, 2020). "Furthermore, IL23R, GnRHR, and beta-catenin, linked to the GnRH pathway, were upregulated in patient-derived tumour tissue samples and their expression correlated to several unfavourable clinical parameters." (PMID 22173670, 2012). "GNRHR is expressed in several peripheral organs, including the uterus, the placenta, the ovaries, the testes, the prostate gland and various tumour types." (PMID 38348415, 2024). "High tumor expression of LHCGR and GNRHR in APAs with CTNNB1 (and GNA11/Q) mutations has been a rationale for the link between the disease onset and pregnancy, menopause, or puberty." (PMID 38505749, 2024). "In agreement with previous studies, LHCGR and GNRHR mRNA levels were also elevated within the tumor compared with those in adjacent normal adrenal (148-fold and 56-fold, respectively)." (PMID 38505749, 2024). "Our present case also showed elevated expression of LHCGR and GNRHR mRNA in the tumor compared with that in adjacent adrenal." (PMID 38505749, 2024). "We have previously shown that GV1001 as a GnRHR biased ligand, suppresses testosterone production as well as tumor growth of LNCaP xenograft in vivo." (PMID 34743733, 2021). "Of interest, GnRHR is expressed in many tumor tissues in which SET has been involved in the tumor progression and aggressiveness." (PMID 30052687, 2018). "We need to consider the relationship between GNRHR expression and tumor proliferation leading to APA." (PMID 27196470, 2016). "Thus, in this study, GnRHR was selected as the tumor target, and the GnRH derivative was used as the targeting carrier of the fluorescent probe." (PMID 40563508, 2025). "Furthermore, both the primary tumor in the foot pads and the metastatic lymph nodes presented positive GnRHR expression, providing recognition and binding sites for GnRHa-PEG-Rh760." (PMID 40563508, 2025). "In this scenario, measurement of GnRHR density in malignant breast tissue may be useful as a surrogate marker to predict the tumor responsiveness to GnRHa administration." (PMID 23176180, 2012). "Thus, GnRH/GnRHR transcripts packaged in extracellular vesicles could be an unexploited mechanism to affect tumor progression in humans." (PMID 29312140, 2017). "This study was cross-sectional, and then we could not establish a causal relationship among GNRHR expression, aldosterone production, and tumor progression." (PMID 27196470, 2016). "GnRHR can also bind to gemcitabine, producing a molecule that is metabolically superior to the gemcitabine molecule (GSG) and inhibits tumor progression in CRPC animal models." (PMID 41347146, 2025). "Clinically, the low expression of GnRHR or FOXO1 and high expression of AKT correlate with tumor aggressiveness and unfavorable clinical outcomes, suggesting their utility as novel prognostic biomarkers in EOC patients." (PMID 41458598, 2025). "Taken together, these results suggest that GnRHR, FOXO1 and AKT are potentially dynamic regulators of tumor behavior and potentially represent promising therapeutic targets and prognostic indicators for EOC." (PMID 41458598, 2025). "SF-1, GnRHR, LH, and FSH were positive in various proportions of cells within the tumor, whereas GH was positive in all cells throughout the tumor (Data not shown)." (PMID 38954291, 2024). "Many primary and metastatic tumor cells overexpress regulatory peptides, such as human epidermal growth factor receptor (HER-2), gonadotropin-releasing hormone receptor (GnRH-R), transferrin receptor (TfR), etc., to varying degrees." (PMID 38399294, 2024). "One tumour with a CTNNB1-mutation was found to have substantially higher expression of both GNRHR and LHCGR than the other studied tumours." (PMID 31000732, 2019).
tumor (continued). "Since the expression of LHB and GNRHR is related to NR5A1 in both Subtype 1 sPitNETs and gonadotroph PitNETs, other genes regulate by this TF turn out to be differentially expressed in these tumor types." (PMID 40813692, 2025). "The UMAP plots showed that the LHB, GNRHR, TGFBR3L, FOSB and SCGN genes were highly expressed mainly in the epithelial cells of the normal group, while their expression was low in the epithelial cells of the tumour group." (PMID 39548559, 2024). "GnRHR is known to transmit signals via beta-catenin, the key signalling molecule of the canonical Wnt pathway, whereas growth factors and inflammatory factors have been suggested to activate the Wnt pathway in CRC to stimulate the mobility of tumour cells." (PMID 22173670, 2012). "However, the pathophysiologic role of high tumor expression of LHCGR and GNRHR mRNA in our case is unclear since her disease onset was not directly associated with pregnancy or menopause." (PMID 38505749, 2024).
infection (1 paper, 2025). The state of being infected such as from the introduction of a foreign agent such as serum, vaccine, antigenic substance or organism. "As above, in animals harboring both the ovine and murine GnRHR promoters, the AdCAFS288 infection significantly reduced serum FSH levels compared to AdGFP, thus confirming effective neutralization of activin in both transgenic models." (PMID 40801031, 2025).
GNRHR also shares sentences with these, for which no sentence is quoted: glioblastoma (7 papers); uterine fibroids (7); adenomyosis (3); colon carcinoma (3); Uterine leiomyoma (3); breast tumor (2); central precocious puberty (2); coronary heart disease (2); COVID-19 (2); cryptorchidism (2); Glucose intolerance (2); Hypertension (2); hypophysis (2); hypospadias (2); triple-negative breast carcinoma (2); acute myocardial infarction (1); adenocarcinoma (1); adrenocortical tumors (1); atherosclerosis (1); atypical endometrial hyperplasia (1); basal cell carcinoma (1); bladder cancer (1); bladder urinary transitional cell carcinoma (1); brain tumors (1); carcinoids (1); cardiovascular disease (1); choriocarcinoma (1); colorectal tumor (1); cystic fibrosis (1); diabetes insipidus (1).
A further 44 diseases each share a sentence with GNRHR in 1 paper.